ATRX (ATRX chromatin remodeler)
Diseases named in the same sentence as ATRX in open-access papers (continued):
Sharing a sentence is not in itself a finding about the gene and the disease.
α-thalassemia (continued). "Hypomorphic germline mutations in ATRX lead to the α-thalassemia/mental retardation X-linked syndrome." (PMID 25077668, 2014). "A unique kind of modifying effect is exemplified by α-thalassaemia/mental retardation syndrome, caused by mutations of the ATRX gene." (PMID 23820649, 2013). "The severity of α-thalassemia resulting from ATRX deficiency correlates with α-globin VNTR length, recapitulating features of diseases associated with trinucleotide repeat instability." (PMID 23637633, 2013). "Deficiencies in ATRX are associated with an X-linked genetic disease characterized by α-thalassemia and mental retardation." (PMID 23637633, 2013). "We performed whole exome sequencing in 4 LGGs, followed by focused resequencing in an additional 28, and found a high incidence of mutations in the ATRX gene (α thalassemia/mental retardation syndrome X-linked)." (PMID 23104868, 2012). "We show here that, the α-thalassemia/mental retardation X-linked protein (ATRX) is essential for the maintenance of chromosome stability during female meiosis." (PMID 20885787, 2010). "The α-thalassemia/mental retardation X-linked protein (ATRX) is a chromatin-remodeling factor known to regulate DNA methylation at repetitive sequences of the human genome." (PMID 20885787, 2010). "Mutations in the ATRX protein result in downregulation of the α-globin locus, leading to thalassemia, and potentially contribute to gene expression abnormalities through disrupted transcription and chromatin structure, causing developmental malformations and intellectual disabilities." (PMID 40546613, 2025). "With rare exceptions, TERT promoter mutations, which lead to an increase in telomerase expression, and inactivating mutations in the thalassemia/mental retardation syndrome X-linked (ATRX) gene, are mutually exclusive, and are associated with different molecular tumor subclasses." (PMID 34558656, 2022). "Importantly, the association of PTMA with poor OS was independent of other clinical markers, including the immunohistochemistry-based assessment of IDH mutation, α-thalassemia/intellectual disability syndrome X-linked (ATRX)." (PMID 35297481, 2022). "The next important step in DAXX studies was the discovery of functional interactions between DAXX and the chromatin-remodeling protein ATRX—an ATP-dependent helicase, mutations in the gene of which cause the X-linked mental retardation syndrome associated with α-thalassemia." (PMID 33525665, 2021). "Apart from that of the known molecular marker IDH1, we found that the status of cell division cycle 27 (CDC27), podocon (PODN), α-thalassemia/mental retardation syndrome X-linked (ATRX) and ryanodine receptor type 1 (RYR1) was significantly different between the two subgroups (P<0.05)." (PMID 34025640, 2021). "ATRX syndrome, which has been associated with ATRX mutations is characterized by a complex phenotype, including serious impairment of psychomotor development, facial dysmorphism, genital anomalies and α thalassemia." (PMID 33173999, 2020). "The ATRX gene was first discovered through a study assessing patients with the x-linked mental retardation (MR) syndrome (ATRX syndrome) presenting with α-thalassemia, severe psychomotor impairments, urogenital abnormalities, and patterns of characteristic facial dysmorphism." (PMID 29034211, 2017).
α-thalassemia (continued). "The only target of ATRX identified to date is α globin which is downregulated in patients with germline or somatic ATRX mutations, including α-thalassemia myelodysplastic syndrome, although evidence that ATRX directly binds to the α globin locus is still lacking." (PMID 18842153, 2008). "Thus, the length of the ψδ VNTR could explain the incomplete penetrance of α-thalassaemia noted in individuals with identical ATRX mutations." (PMID 23820649, 2013). "Mutations on the ATRX gene (Cd39(C→T), IVS I-5(G→C), c.848T > C, and c.623delA) were found to contribute to α-thalassemia-like phenotype and have been reported in the Saudi population." (PMID 37950286, 2023). "Indeed, hypomorphic germ line mutations of human ATRX gene give rise to the ATRX syndrome, a disorder characterized by a form of X-linked severe intellectual disability, facial dysmorphism, reduced expression of the α-globin genes (α-thalassemia), urogenital dysfunction, and skeletal abnormalities." (PMID 34062956, 2021). "IDH1R132H was negative, and alpha‐thalassemia/mental retardation, X‐linked (ATRX) demonstrated the loss of nuclear expression." (PMID 40880425, 2025). "Therefore, mutations in ATRX are significant contributors to alpha thalassemia myelodysplastic syndrome (ATMDS), which is a severe form of α-thalassemia." (PMID 39479502, 2024). "Although the connection between ATRX mutations and α-thalassemia is not completely clear, the ATRX protein was found to be a transcriptional regulator affecting α-globin gene expression." (PMID 34713239, 2020). "We also looked for alpha-thalassemia/mental retardation (ATRX) gene mutation status, since ATRX loss by immunohistochemistry is characteristic, but not required for diagnosis of diffuse astrocytoma, IDH-mutant by the WHO." (PMID 28030632, 2016). "However, the mean difference did not reflect the genetic status of 1p/19q, α-thalassemia/mental retardation syndrome-X-linked (ATRX) gene, or O6-methylguanine-DNA-methyltransferase (MGMT)." (PMID 40352771, 2025). "A missense mutation of one Alpha Thalassemia/Mental Retardation Syndrome X-Linked allele and a splice site mutation with varying allele frequency were also detected; however, there was no immunohistochemical loss of ATRX expression." (PMID 36380356, 2022). "Previously we have shown that the severity of α-thalassaemia in ATR-X syndrome is determined, to a large extent, (accounting for ~60% of the variance) by the length of a G-rich variable number tandem repeat (ψζ) lying upstream of the α-globin cluster to which ATRX binds." (PMID 35710802, 2022).
pancreatic neuroendocrine tumor (56 papers, 2012 to 2026). Pancreatic endocrine tumor, also known as pancreatic neuroendocrine tumor (PNET), describes a group of endocrine tumors originating in the pancreas that are usually indolent and benign, but may have the potential to be malignant. "Since the discovery of a close association between ATRX and DAXX mutations and ALT in pancreatic neuroendocrine tumors, an ever‐growing number of studies have investigated the mechanistic link between ATRX loss and ALT establishment." (PMID 37499040, 2023). "First, DAXX and ATRX mutations are mutually exclusive in pancreatic neuroendocrine tumors, indicating their shared function is required for tumor suppression." (PMID 37633949, 2023). "This is roughly in line with a previous study of 20 pancreatic NET G3 where 3 ATRX and 7 DAXX mutations were found." (PMID 34647903, 2021). "It is reported that ATRX mutation is a poor prognostic factor in pancreatic neuroendocrine tumors (pNETs) 20, hepatic angiosarcomas 21, and leiomyosarcoma 22, 23, while it is found to be a good prognostic factor in glioma 24, and cervical cancer." (PMID 34729095, 2021). "Of note, 10 of the 11 DAXX alterations were found in pancreatic endocrine tumors, while ATRX mutations were seen in a wider variety of entities." (PMID 32024817, 2020). "ATRX gene mutations were first discovered in pancreatic neuroendocrine tumors, and subsequently in other cancer subtypes, including gliomas." (PMID 30073207, 2018). "In pancreatic neuroendocrine tumors (PanNETs) ATRX, DAXX, and MEN1 are commonly mutated (A-D-M mutant PanNETs)." (PMID 30315258, 2018). "In oncology, ATRX gene mutations were first discovered in pancreatic neuroendocrine tumors (PanNETs), where mutations of ATRX and DAXX are associated with a better prognosis." (PMID 29359122, 2017). "The genes encoding the chromatin remodeling complex DAXX:ATRX are frequently mutated in pancreatic neuroendocrine tumors; however, the underlying mechanisms of how mutations contribute to tumorigenesis are only partially understood, in part because of the lack of relevant preclinical models." (PMID 35976056, 2022). "The first tumor to observe ATRX or DAXX loss mutations is pancreatic neuroendocrine tumors." (PMID 36428674, 2022). "Both the mutations in MEN1 and DAXX/ATRX suggest that targeting these epigenetic mechanisms with small molecule compounds may be a viable approach to developing new therapeutics for pancreatic NETs." (PMID 29255447, 2017). "Furthermore, in pancreatic neuroendocrine tumors, aberrant ATRX and DAXX expression was associated with lymph node metastasis and distant metastasis by causing the abnormal lengthening of telomeres, and was also associated with shorter disease-free survival and disease-specific survival." (PMID 34272397, 2021). "Genomic studies focusing on pancreatic NETs highlighted mutations in MEN1, DAXX, ATRX, and targets in mTOR pathway." (PMID 41483302, 2026). "Based on prior data, the most prevalent mutations in pancreatic neuroendocrine tumors include those in MEN1 (44%), DAXX/ATRX (43%) 17, 18, and genes related to the mTOR pathway." (PMID 41323792, 2025). "Next, we found that mutations in MEN1, PTEN and ATRX or DAXX co-occur with a high statistical likelihood, suggesting that co-mutation of those genes is one of the core determinants of pancreatic neuroendocrine tumors pathogenesis." (PMID 38609433, 2024). "ATRX inactivating mutations are commonly observed among different tumor types, while DAXX mutations are primarily associated with pancreatic neuroendocrine tumors (PanNETs)." (PMID 39224814, 2024). "Here, we demonstrated that combined loss of MEN1, ATRX, and PTEN, tumor suppressors commonly mutated in human PanNETs, triggers the development of high-grade pancreatic neuroendocrine tumors in mice." (PMID 38609433, 2024). "Patients with primary pancreatic NETs and loss of DAXX, ATRX, ARID1, and/or CDKN2A had reduced survival times." (PMID 37387515, 2023).
pancreatic neuroendocrine tumor (continued). "Recent sequencing studies revealed that pancreatic neuroendocrine tumors (PanNETs) are driven by somatic loss-of-function mutations in epigenetic regulators, with recurrent mutations in MEN1 (38%), DAXX (23%), and ATRX (10%)." (PMID 37633949, 2023). "Inactivating somatic mutations in ATRX, DAXX, and MEN1 represent the major mutations encountered in pancreatic NETs, but are much less frequent in their thoracopulmonary counterparts, indicating distinct site-dependent genetic pathways driving these tumors." (PMID 36690805, 2023). "Certain mutations in KLKB1, mutated in one of five CT-pNENs, cause prekallikrein deficiency, and KLKB1 was mutually exclusive with ATRX, DAXX, and MEN1 of pancreatic neuroendocrine tumors (PanNets)." (PMID 37771441, 2023). "The exome sequencing of ten sporadic pancreatic neuroendocrine tumors (PanNETs) identified recurrent and mutually exclusive loss-of-function mutations in DAXX and ATRX for the first time." (PMID 35976056, 2022). "ATRX and MEN1 genes are both involved in chromatin remodelling and have been identified as the most frequent somatic mutation in pancreatic NETs." (PMID 35323929, 2022). "There is a strong correlation between ATRX and DAXX mutations and an alternative lengthening of telomeres (ALT) phenotype in pancreatic NET." (PMID 33555458, 2021). "In NET G3, which is most frequently occurring in the pancreas, most alterations were also seen in pancreatic primaries, including mutations in MEN1 (33%), ATRX (25%) and DAXX (25%; within the subgroup of pancreatic NET G3)." (PMID 34647903, 2021). "Although the loss of ATRX/DAXX and ALT in pancreatic NET is generally associated with tumor aggressiveness and reduced progression-free survival, these features are associated with better overall survival in the sub-cohort of metastatic patients." (PMID 33555458, 2021). "Pancreatic NET also exhibit recurrent mutations in a relatively limited number of genes, including the tumor suppressor gene MEN1, as well as ATRX and DAXX, genes implicated in chromatin remodeling." (PMID 32477464, 2020). "Conversely, inactivating mutations in DAXX and ATRX and in MEN1 are exclusively found in pancreatic NET." (PMID 32492939, 2020). "Chromosome instability and reduced survival have been associated with the ATRX and DAXX mutations in pancreatic NETs as well." (PMID 31527438, 2019). "Pancreatic neuroendocrine tumors are also characterized by recurrent mutations in a relatively limited number of genes, which include tumor suppressor gene MEN1, as well as ATRX and DAXX, genes implicated in chromatin remodeling." (PMID 28903345, 2017). "Recently, pancreatic NETs were characterized as having recurrent somatic mutations in MEN1, DAXX, ATRX, TSC, and PTEN on the basis of exome sequencing of 10 pancreatic NETs." (PMID 26684240, 2016). "When combined with a DAXX or ATRX mutation, MEN1-inactivated pancreatic NETs have a poor prognosis." (PMID 40026252, 2025). "Other studies in patients with MEN1-related pancreatic NETs suggest that DAXX/ATRX mutations are not driver mutations, but rather later events in the pathogenesis of NET development." (PMID 29255447, 2017). "Notably, the loss of ATRX/DAXX expression is an independent prognostic biomarker for decreased RFS in non-functional pancreatic neuroendocrine tumors." (PMID 36428674, 2022).
pancreatic neuroendocrine tumor (continued). "Pancreatic NETs frequently exhibit changes in genes such as MEN1, DAXX, ATRX, TSC1, TSC2, CDKN1A, and CDKN1B, along with alterations in CDKN2A and SETD2 in metastatic lesions." (PMID 41426335, 2025). "In neuroendocrine pancreatic tumors, DAXX, the histone chaperone partner of ATRX, is frequently altered in ALT + cases, and has similarly been implicated in pHGG." (PMID 41422096, 2025). "The authors also found that pancreatic NETs exhibit recurrent genetic inactivation of MEN1, ATRX, and DAXX and the activation of the PI3K/mTOR pathway." (PMID 40026252, 2025). "Pancreatic NETs have variations in DAXX, ATRX, PTEN, and TSC2, whereas GI-NETs have identified CDKN1B and RASSF1A as the recurrent mutations." (PMID 29255447, 2017). "The most frequent gene alterations in pancreatic NETs were MEN1 and DAXX/ATRX." (PMID 37387515, 2023). "Furthermore, the gene panel is restricted to 73 genes failing to test for MEN1, ATRX or DAXX, which are clinically important in pancreatic NET." (PMID 32477464, 2020). "In a case report on one patient with metastatic pancreatic NET G−3, the whole-genome sequencing of liver metastases exhibited a TSC1-disrupting fusion, showed a novel CHD7–BEND2 fusion, but lacked any somatic variants in ATRX, DAXX, and MEN1." (PMID 32492939, 2020). "While loss-of-function mutations in the ATRX gene have been implicated as a driving force for a variety of pediatric brain tumors, as well as pancreatic neuroendocrine tumors, the role of ATRX in gene regulation and oncogenic development is not well-characterized." (PMID 32218364, 2020).